BAG1 (BAG cochaperone 1)
Diseases named in the same sentence as BAG1 in open-access papers (continued):
Sharing a sentence is not in itself a finding about the gene and the disease.
infection (20 papers, 2011 to 2025). The state of being infected such as from the introduction of a foreign agent such as serum, vaccine, antigenic substance or organism. "We stained the sections with antibodies against SAG1 and BAG1 to determine the parasite stages, or with polyclonal antibodies against T. gondii for a general overview of the infection." (PMID 39903779, 2025). "SAG1 and BAG1 mRNA presence in brain homogenates in which T. gondii gDNA was detected, 7d and 10d post infection." (PMID 38912206, 2024). "The bradyzoite-specific antigen BAG1 can induce specific Th cell responses, and humoral reactions against bradyzoites and tissue cysts occur primarily in the early stages of infection." (PMID 39080770, 2024). "These heterogeneities in host cell response to infection encouraged us to examine the difference in parasitic gene expression in the BAG1+HR-IvL or BAG1+#A–#F subsets." (PMID 35372115, 2022). "BAG1+ cells in the HR-IvL subset showed infection-triggered altered transcription and upregulated E2F target pathways with higher expression levels of c-Myc, along with a higher enrichment score for the MYC_Targets_V1 pathway." (PMID 35372115, 2022). "BAG1 demonstrates between a 5-10-fold increase in expression at 28 and 56 days post infection, supporting the presence of bradyzoites in the brain at these later chronic stages." (PMID 33816350, 2021). "Transcripts for the bradyzoite antigen BAG1 were less abundant during RH infection compared to PTG infection in both wild type and MyD88 KO." (PMID 33622246, 2021). "We observed anti-beta amyloid signal in the brain cortex at days 30 and 60 post infection and found BAG-1 signal in comparable regions of the cortex." (PMID 29471842, 2018). "We observed increasing frequency of T. gondii cysts stained with BAG1 antibody and/or T. gondii antigen at days 15, 30, 60, and 90 post infection." (PMID 29471842, 2018). "This is consistent with our findings that EGS in HFF forms cysts by 24 hours, characterized by BAG1, and Dolichos staining at 24, 48, and 96 hours after infection." (PMID 27412848, 2016). "The diagnostic value of BAG1 protein has been evaluated with sera from patients whom the time of seroconversion was known and IgG antibodies reacted with BAG1 protein as early as one month after infection in these samples." (PMID 25268351, 2014). "Results of RT-PCR showed that SAG1 and BAG1 genes were expressed in the brain samples of mice fifty days post infection." (PMID 23682258, 2013). "CHIP, BAG-1 and HspBP1, respectively, were depleted in mouse BMDCs using specific siRNAs, followed by infection with a recombinant adenovirus that expresses the immune dominant SIINFEKL peptide of ovalbumin fused to luciferase and GFP (Ad-LOG)." (PMID 21283720, 2011). "The earliest detection of BAG1 was seven days post infection." (PMID 38912206, 2024). "A total of 30 mice were anti-BAG1 positive 4 weeks post-infection." (PMID 30519229, 2018). "Moreover, there was co-localization of 6E10 and BAG1-positive T. gondii cysts as early as day 15 post infection." (PMID 29471842, 2018). "As such, the ENO1 and BAG1 genes, which are well known to be expressed distinctively in the bradyzoite stage during the chronic phase of infection, were highly enriched in the repressive mark H3K9me3 but they were also unexpectedly enriched in the gene activation hallmark H3K14ac." (PMID 29101771, 2017). "Therefore for subsequent experiments, we used anti-BAG1 positive mice 6-8 weeks post infection as chronically infected animals." (PMID 27895319, 2016). "All infected mice turned anti-BAG1 positive 10 weeks after infection." (PMID 27895319, 2016). "The sera of mice became anti-BAG1 positive as early as 6 weeks post infection." (PMID 27895319, 2016).
infection (continued). "The low abundance of SAG-1 and high abundance of BAG-1 between 28 day post-infection and 10 day post infection time points also suggests that tachyzoites are the primary stage present at 10 days post-infection, while the majority of parasites at 28 days post-infection are in the bradyzoite stage." (PMID 25240600, 2014). "This suggests infection with T. gondii stimulates the immune response and/or immune cell recruitment into the brain even when the majority of parasites are in the encysted stage, as seen by the increased abundance of BAG1 and decreased abundance of SAG1." (PMID 25240600, 2014). "At 3 days post-infection, parasites were fixed, mCherry fluorescence was quenched using methanol, and then parasites were stained with SAG1 and BAG1 antibodies (Figs 4Ai-iii)." (PMID 39903779, 2025). "Fold change analysis of bradyzoite associated genes reveal significant increases of the bradyzoite specific SRS35A, BAG1 and LDH2 as infection progresses." (PMID 33816350, 2021). "Most bradyzoite-specific genes such as SRS35A, BAG1, and LDH2 accumulate over time and remain dominant as infection progresses with increased presence of late-stage bradyzoites and support a maturation of cysts in the brain." (PMID 33816350, 2021). "Serum IgG antibodies specific to bradyzoite BAG1 and MAG1 proteins, were detected early after infection in human sera and in mice orally infected with cysts." (PMID 33324583, 2020). "In the present study, BALB/c and C57BL/6 mice were infected and in chronic phase of infection they were immunosuppressed with DXM to observe the TgHSP70, SAG1 and BAG1 expression in the brain." (PMID 24801069, 2014). "However, BAG1, a bradyzoite antigen and MAG1 a matrix antigen, were shown to induce an early humoral and cell-mediated immune responses upon human infection." (PMID 33324583, 2020). "While the injections did not significantly alleviate caecal lesions caused by infection of E. tenella, this result indicated that anti-BAG1 serum and anti-ENDOUL serum could partially inhibit infection of E. tenella in chickens." (PMID 32678057, 2020). "We observed no 6E10 or BAG-1 signal in the brains at day 60 post infection, indicating that the antibodies were specific." (PMID 29471842, 2018). "In this study, although BAG1 and ENDOUL were determined as host receptors of EtMIC3 for Eimeria invasion, their antiserum did not completely block subsequent infection by E. tenella parasite in vivo." (PMID 32678057, 2020). "With the progression of infection it was observed a decrease of SAG1 and an increase in BAG1 mRNA expression, and DXM treatment was not able to augment the SAG1 mRNA expression in BALB/c mice." (PMID 24801069, 2014).
neurodegenerative disease (2 papers, 2011 to 2024). A disorder of the central nervous system characterized by gradual and progressive loss of neural tissue and neurologic function. "Therefore, the BAG1 to BAG3 protein ratio dictates a proteasome to autophagy switch in neurodegenerative diseases and has been shown to be critical for HSC homeostasis and aging." (PMID 39560992, 2024). "The reduced expression of BAG1 isoforms, decreased BAG1/BAG3 ratio, and association of BAG3 with NE supports our hypothesis of alternate NE peptide–induced aggrephagy machinery in these cells, a mechanism similar to neurodegenerative diseases." (PMID 39560992, 2024).
gynecological tumor (1 paper, 2017). "Genes that highly expressed in EAEMT compared with EA type cells were TCEAL4, BAG1, VAT1, and GPI which are known to be gynecological tumor markers." (PMID 29079795, 2017).
BAG1 also shares sentences with these, for which no sentence is quoted: glioblastoma (4 papers); Parkinson disease (3); Alzheimer disease (2); astrocytoma (1); B-cell lymphoma (1); breast disease (1); Burkitt lymphoma (1); B‐cell acute lymphoblastic leukaemia (1); clear-cell renal cell carcinoma (1); cognitive deficits (1); depression (1); Down syndrome (1); laryngeal carcinoma (1); laryngeal tumours (1); lymph node metastasis (1); neurological diseases (1); oral cancer (1); ovarian carcinoma (1); thymic carcinoma (1); tongue SCC (1); toxoplasmosis (1); triple-negative breast carcinoma (1); uterine cancer (1); viral infections (1).